LINC01742 (long independently transcribed non-coding RNA 1742)
Gene: Long non-coding RNA gene on chromosome 20 (58,001,438 to 58,004,648, forward strand). Ensembl gene ENSG00000275852.
Diseases named in the same sentence as LINC01742 in open-access papers:
LINC01742 is named in the same sentence as 1 disease in open-access papers, as found by Europe PMC text mining. Sharing a sentence is not in itself a finding about the gene and the disease. The quoted sentences say what the papers report.
breast carcinoma (1 paper, 2021). "The results suggested that metastasis associated RNAs, including AHRR, TTC34, CNTRL, ANKRD52, BCAR1, TMEM151B, PANX2, hsa-miR-105-5p, hsa-miR-4435, hsa-miR-5691, hsa-miR-92a-1-5p, and LINC01742 could serve as the prognostic biomarkers of breast cancer patients." (PMID 34055638, 2021). "Inversely, breast cancer patients with higher expression level of AHRR, ANKRD52, BCAR1, PANX2, hsa-miR-105-5p, hsa-miR-4435, and LINC01742 showed the lower OS." (PMID 34055638, 2021).